RAC1 (Rac family small GTPase 1)
Diseases named in the same sentence as RAC1 in open-access papers (continued):
Sharing a sentence is not in itself a finding about the gene and the disease.
bacterial infection (10 papers, 2012 to 2025). "While our multiple methods demonstrate the APE1 and Rac1 interaction, exactly how the interaction is initiated by bacterial infection needs to be established in future studies." (PMID 33603730, 2020). "Our documentation of regulation of bacterial infections by a Wnt5A—Rac1—Disheveled mediated autophagy circuit unveils an as yet uncharacterized component of host pathogen interactions in the innate immune defense program." (PMID 29686674, 2018). "Macrophage-mediated containment of bacterial infection in our study is dependant on Wnt5A-induced Rac1/Disheveled activation and cytochalasin D inhibitable actin assembly, which is associated with ULK1 kinase activity and LC3BII accumulation." (PMID 29686674, 2018). "APE1 is a negative regulator of oxidative stress in the gastrointestinal epithelium during bacterial infection by modulating Rac1 and Nox1." (PMID 26761793, 2016). "Further studies examining the links between Rac1 and inflammasomes are required to fully understand their interaction in bacterial infections." (PMID 22276187, 2012). "To do so, we first compared Rac1•GTP levels in PMNs and PBMCs from the uninfected patients (81 included in the final analysis) to those found in 61 serial samples drawn from 28 patients with blood culture-positive bacterial infections." (PMID 40041147, 2025). "The expression of B2m, Ctsl, Calr, and Pdia3 suggests efficient antigen processing and presentation process, and the upregulation of Rac1, and Cd14 indicats the involvement of TLR2 and TLR4, which are essential for Th1/Th17 responses elicited by wPVs or bacterial infection." (PMID 34759909, 2021). "Together, these data support the concept that through its molecular interactions with Rac1, APE1 provides negative feedback on Nox1 and oxidative responses in the gastrointestinal epithelium during bacterial infection." (PMID 26761793, 2016).
neurological diseases (8 papers, 2018 to 2024). "Consistent with Rac1’s important roles in synaptic signaling, mutations of Rac1 or alterations to its signaling pathways are associated with a variety of neurological disorders." (PMID 38562715, 2024). "Rac1, a Rho GTPase, is a critical regulator of actin signaling cascades, and human mutations in Rac1 are associated with neurological disorders." (PMID 36214784, 2022). "Human mutations of Rac1 may affect synaptic strength at many different synaptic connections and potentially alter the excitation-inhibition balance and synaptic information processing in neuronal circuits associated with neurological disorders and addiction." (PMID 36214784, 2022). "Abnormal Rac1 expression and activity have been observed in multiple neurological diseases." (PMID 33299404, 2020). "Another Rab protein that could be involved, together with Rac1, in neurological diseases is Rab7a." (PMID 31035701, 2019).
psychiatric disorder (7 papers, 2016 to 2023). A disorder characterized by behavioral and/or psychological abnormalities, often accompanied by physical symptoms. "Rac1 activity is also associated with Huntington’s disease (HD) that usually causes movement and cognitive and psychiatric disorders with an extensive spectrum of symptoms and signs." (PMID 32362820, 2020). "Together, these findings reveal a role for brain-region specific differences in the dysregulation of Rac1-to-cofilin signaling in the effects of repeated stress on two brain areas that are implicated in the emotional and cognitive symptoms of stress-related psychiatric disorders." (PMID 35592113, 2022). "The three main Rho GTPases—RhoA, Rac1, and Cdc42, together with their modulators, are known to be involved in many psychiatric disorders that affect the amygdala′s fear conditioning mechanism." (PMID 32858950, 2020). "Since astrocytes can control neuronal RAC1 signaling through TSP-α2δ-1, understanding the regulatory mechanism of the TSP-α2δ-1-RAC1 pathway in astrocytes may uncover new potential therapeutic targets for psychiatric disorders such as ASD in the future." (PMID 34658786, 2021).
retinopathy (6 papers, 2016 to 2023). "A total of two experimental studies have shown that the transcriptional activation of the RAC1 gene in diabetic mice has been found to contribute to mitochondrial damage and retinopathy, suggesting at least a causal role of this gene in diabetic complications." (PMID 36979960, 2023). "Rac1-Nox2 activation is also associated with aberrant retinal neovascularization, and its inhibition, during the advanced stages of retinopathy has potential to slow down neovascularization, a hallmark of proliferative diabetic retinopathy." (PMID 34063353, 2021). "Given the importance of Crb1 in regulating Rac1 and limiting the production of photoreceptor superoxide, we sought to explore the effect of neonatal hyperoxia and neonatal proliferative retinopathy on mice carrying the rd8 mutation." (PMID 28671996, 2017). "For example, Rac1-Nox2 signaling is inhibited by statins, which inhibits 3-hydroxy-3-methylglutaryl coenzyme A, and a population-based cohort study in Taiwan has shown promising results in decreasing the risk retinopathy and its progression." (PMID 34063353, 2021). "Furthermore, Rac1 is also associated with aberrant retinal neovascularization, and its inhibition during the advanced stages of retinopathy would also slow down neovascularization, a hallmark of proliferative diabetic retinopathy." (PMID 31277234, 2019). "Inhibition of GEF Vav2, by its pharmacological inhibitor EHop, prevents activation of Rac1-Nox2-ROS signaling and inhibits mitochondrial damage and the development of retinopathy in diabetic mice." (PMID 34063353, 2021).
brain disorder (5 papers, 2020 to 2025). A disease affecting the brain or part of the brain. "In light of the pivotal role of Rac1 in learning and memory, this small GTPase and its downstream molecules have also been associated with a range of brain disorders." (PMID 35592113, 2022). "Notably, more (e.g. CA) or less (e.g. DN) Rac1 activity in these neurons is potentially as the therapeutic target to promote or prevent this type of forgetting, which is often associated with social dysfunctions in many brain disorders." (PMID 40158067, 2025). "We owe it to the patients to change our minds to ponder other possibilities beyond the known pathological mechanisms and potential therapies for memory-related brain disorders, such as Rac1-dependent intrinsic forgetting." (PMID 37445914, 2023). "Above all, Rac1 activity in the brain may play a critical role in neuronal morphological abnormalities and memory-related brain disorders." (PMID 37445914, 2023). "Defining the details of Rac1 signaling processes may provide potential new therapeutic strategies and molecular targets to treat AD and related brain disorders." (PMID 35936771, 2022). "Taking into consideration the core function of Rac1 in synaptic actin dynamics, cytoskeleton rearrangements and memory management, it is not surprising that Rac1-dependent intrinsic forgetting may play a fundamental (or partial) role in memory deficits among several brain diseases." (PMID 37445914, 2023). "Here, we only discuss the relationship between Rac1-dependent intrinsic forgetting and these brain disorders in this perspective, not other aspects of the disease." (PMID 37445914, 2023).
cardiac disease (5 papers, 2016 to 2025). "Here, we review what is known about Rac1 signaling in cardiomyocytes, discuss how these signaling pathways can potentially be targeted for the treatment and prevention of cardiac disease, and propose areas of Rac1 signaling that warrant further exploration." (PMID 41333012, 2025). "Future studies should be directed at understanding the regulatory enzymes and spatial organization that govern Rac1 signaling in cardiomyocytes to uncover novel signaling circuitry for potential targeting in cardiac diseases." (PMID 41333012, 2025). "Cardiomyocyte-specific transgenic mice overexpressing zDHHC3 show cardiac disease, and S-acyl proteomics identified the small GTPase Rac1 as a novel substrate of zDHHC3." (PMID 37926281, 2023). "Rac1 is activated in response to a myriad of hypertrophic stimuli, including but not limited to angiotensin II (AngII), phenylephrine (PE), endothelin-1 (ET-1), stretch, pressure overload and in multiple animal models of hypertension-induced heart disease." (PMID 41333012, 2025). "Inhibition of Rac1 S-palmitoylation may thus provide an alternative therapeutic approach for cardiac disease treatment by inhibiting maladaptive Rac1 signaling at the sarcolemma." (PMID 37926281, 2023). "Direct assessment of the effect of cardiomyocyte-specific Rac1 deletion on cardiac structure, function, and signaling in response to established physiologic hypertrophy models such as chronic swimming and running would provide important context to the rationale of targeting Rac1 for heart disease." (PMID 41333012, 2025). "Moreover, Rac1 and its effectors have important roles in cardiomyocyte electrophysiology and arrhythmogenesis and therapeutic approaches directly targeting Rac1, NOX2, PAK1, or apoptosis signal-regulating kinase 1 (ASK1) have shown promise in preclinical models of cardiac disease." (PMID 41333012, 2025).
neurodegenerative disease (5 papers, 2013 to 2023). A disorder of the central nervous system characterized by gradual and progressive loss of neural tissue and neurologic function. "Intriguingly, despite the apparent protective role of Rac1 in neurodegenerative diseases, SOD1 mutations in microglia have been shown to enhance Rac1 activity." (PMID 27442895, 2017). "As such, deregulation of Rac1 signaling is also implicated in neurodegenerative diseases." (PMID 27442895, 2017). "Additionally, alsin has been shown to antagonize the effects of SOD1 mutants on motor neuronal death in a Rac1-dependent manner, further highlighting the protective role of Rac1 in neurodegenerative diseases." (PMID 27442895, 2017). "In addition, dysfunctions of Rac1-dependent intrinsic forgetting may contribute to memory deficits in neurological and neurodegenerative diseases." (PMID 37445914, 2023). "Although alsin can function as a GEF for both Rab5 and Rac1, alsin colocalizes with Rac1 in the growth cones of neurons and regulates Rac1 signaling and neurite outgrowth through its intrinsic GEF activity, thus suggesting a link between Rac1 disruption and neurodegenerative disease." (PMID 25339865, 2014).
colon (3 papers, 2019 to 2025). "In this study, we present the first in vivo evidence for a role of the Rac1-specific GAP β2-chimaerin in Apc-driven colon carcinogenesis." (PMID 40005135, 2025).
hematological malignancies (3 papers, 2017 to 2022). "Protein Rac1 (RAS-related C3 botulinum toxin substrate is considered a prime target to combat a variety of solid tumors and certain onco-hematological malignancies." (PMID 35740379, 2022). "All this evidence supports the therapeutic potential of target-based therapies against Rac1-GTPase in hematological malignancies." (PMID 29228706, 2017). "Interestingly, Rac1 inhibition displayed selective activity on patient-derived leukemic cells having no cytotoxic effect on normal monocytic and lymphocytic cells, representing a promising pharmacological and selective compound for the treatment of hematological malignancies." (PMID 29228706, 2017).
immunodeficiency (3 papers, 2017 to 2021). Failure of the immune system to protect the body adequately from infection, due to the absence or insufficiency of some component process or substance. "The alteration of RAC1 activity has been shown to be associated with immunodeficiency." (PMID 33406731, 2021). "Therefore, RAC1 keeps critical roles in the maintenance of epithelial homeostasis under both physiological and pathological conditions, but also is a potential therapeutic target against immune diseases." (PMID 33406731, 2021).
infectious disease (3 papers, 2016 to 2022). A disorder directly resulting from the presence and activity of a microbial, viral, or parasitic agent in humans. "However, demonstrating the complexity of Rac1 signaling in infectious diseases, Rac1 is also implicated in the innate immune response." (PMID 27442895, 2017). "Aberrant regulation of Rac1 signaling is also a key feature in a number of infectious diseases." (PMID 27442895, 2017). "Moreover, the question of whether Tiam1/Rac1 signalling in T cells influences the pathogenesis of other autoimmune or infectious diseases is intriguing." (PMID 27725632, 2016).
inflammation (3 papers, 2018 to 2020). Aberrant reaction of the microcirculation characterized by movement of fluid and leukocytes from the blood into extravascular tissues. "However, BPS administration inhibited salt-induced Rac1-MR activation as well as renal inflammation and damage, suggesting that Rac1-MR pathway is involved in anti-inflammatory and renoprotective effects of PGI2." (PMID 32580367, 2020).
adenocarcinoma (2 papers, 2014 to 2023). A common cancer characterized by the presence of malignant glandular cells. "DGKζ protein levels, Rac1 and RhoA activity, and PAK phosphorylation were measured in the non-metastatic SW480 adenocarcinoma cell line and its highly metastatic variant, the SW620 line." (PMID 24646293, 2014).
CNS neoplasms (2 papers, 2014 to 2024). "The finding that merlin regulates SC NPC growth in a Rac1- and ErbB2-dependent manner firmly establishes a central growth control target for NF2-associated spinal ependymoma, and advocate for further studies addressing the potential use of ErbB2 inhibitors to treat these CNS neoplasms." (PMID 24817309, 2014).
metabolic disease (2 papers, 2020 to 2024). A congenital disorder (due to inherited enzyme abnormality) or acquired (due to failure of a metabolically important organ) disorder resulting from an abnormal metabolic process. "According to this crucial role of Rac1 in maintaining glucose homeostasis, dysregulated Rac1 signaling is associated with metabolic disorders." (PMID 39598690, 2024). "Understanding how different exercise intensities affect molecular mechanisms such as Rac1 or PAK1 expression may reveal new therapeutic targets to treat patients with metabolic diseases." (PMID 33329033, 2020).
RAC1 also shares sentences with these, for which no sentence is quoted: breast (4 papers); congestive heart failure (4); hypertrophy (4); coronary artery disease (3); kidney cancer (3); Mental Retardation autosomal dominant 48 (3); acute pancreatitis (2); allergic disease (2); benign breast disease (2); cardiac arrhythmia (2); cerebrovascular disorder (2); cholestasis (2); cleft palate (2); colon adenocarcinoma (2); dengue (2); Encephalopathy (2); Glucose intolerance (2); Hearing impairment (2); Huntington disease (2); hyperlipidemia (2); ischemic cardiomyopathy (2); Miscarriage (2); opioid dependence (2); Papillary Thyroid Cancer (2); spinal cord injury (2); uterine cancer (2); acute myocardial infarction (1); acute respiratory distress syndrome (1); Adams-Oliver syndrome (1); adrenal cancers (1).
A further 118 diseases each share a sentence with RAC1 in 1 paper.